ACAN (aggrecan)
Diseases named in the same sentence as ACAN in open-access papers (continued):
Sharing a sentence is not in itself a finding about the gene and the disease.
heart failure (1 paper, 2014). Inability of the heart to pump blood at an adequate rate to meet tissue metabolic requirements. "Although it has been shown that the large hydrophilic proteoglycans versican and aggrecan reside in the embryonic cardiac ECM, and that versican is expressed in cardiomyocytes and the adult heart, their role in heart failure development is unknown." (PMID 24595230, 2014).
hypothyroidism (1 paper, 2023). Abnormally low levels of thyroid hormone. "WES analysis showed several variants in genes associated with short stature, GH deficiency and hypothyroidism including ACAN, GHR, RNPC3 and TSHR (Table-II)." (PMID 37680843, 2023).
idiopathic scoliosis (1 paper, 2023). A scoliosis with no known cause. "The results of immunohistochemistry confirmed the degeneration of IVD by showing a reduced expression of Aggrecan and Col2A1 in degenerated IVD compared to that of the idiopathic scoliosis group." (PMID 37667246, 2023).
Intellectual disability (1 paper, 2020). "DD was caused by SETD5 mutation inherited from his mother with intellectual disability and growth delay was caused by ACAN mutation inherited from his father with short stature." (PMID 32595695, 2020).
Intraventricular hemorrhage (1 paper, 2023). Bleeding into the ventricles of the brain. "Similarly, there is an upregulation of aggrecan, brevican, neurocan and versican in rabbit pups after intraventricular hemorrhage." (PMID 38025264, 2023).
laryngeal squamous cell carcinoma (1 paper, 2023). A squamous cell carcinoma that arises from the larynx. "During the progression of laryngeal squamous cell carcinoma, aggrecan undergoes significant compositional and structural changes, with a stage-related loss of aggregable aggrecan adjacent to apparently normal cartilage and strong presence in advanced stages." (PMID 36765749, 2023).
leukaemia (1 paper, 2024). "Adipogenesis, chondrogenesis, and osteogenesis differentiation of BM‐MSCs treated with leukaemia sEVs were determined using FABP4, aggrecan and osteocalcin, respectively." (PMID 38499475, 2024). "In addition, we also found some leukaemia‐specific proteins, oncogenes (COL2A1, CLIP1, NUMA1 and GALK1), and stem cell‐regulated proteins (ACAN, VCAN, COMP and PRDX6)." (PMID 38499475, 2024).
multiple sclerosis (1 paper, 2020). A progressive autoimmune disorder affecting the central nervous system resulting in demyelination. "The upregulation of versican V2, aggrecan, and neurocan as CSPGs family members, following multiple sclerosis, was also reported by Sobel & Ahmed (2001)." (PMID 32483473, 2020).
osteochondrodysplasia (1 paper, 2021). A term referring to disorders characterized by abnormalities in the development of bones and cartilage. "Despite the variability of the clinical features related to ACAN mutations, the genetic variation detected in this case, resulted in a rare form of osteochondrodysplasia with short limbs and possible future involvement of the spine and joints." (PMID 34187405, 2021). "Based on the clinical features associated with ACAN mutations a diagnosis of osteochondrodysplasia with short limbs and a possible future involvement of the spine and joints were done." (PMID 34187405, 2021).
Osteochondrosis (1 paper, 2024). Abnormal growth ossification centers in children. "ACAN mutations can cause skeletal disorders such as osteochondrosis and skeletal dysplasia, which affect height." (PMID 39748948, 2024).
otosclerosis (1 paper, 2020). Formation of spongy bone in the labyrinth capsule which can progress toward the stapes (stapedial fixation) or anteriorly toward the cochlea leading to conductive, sensorineural, or mixed hearing loss. "Nevertheless, several reports and family linkage analyses have identified the association between 15q26.1-qter locus and otosclerosis (OTSC1) with ACAN to be one of the candidate genes." (PMID 31841439, 2020). "To date, otosclerosis has not yet been reported in patients with pathogenic ACAN variants." (PMID 31841439, 2020).
ovarian tumors (1 paper, 2016). "In a previous work from our group we observed by immunohistochemistry the presence of aggrecan in the nuclei of ovarian tumors cells." (PMID 27764205, 2016).
parasitic infections (1 paper, 2022). "MMP-9 is implemented in nearly all parasitic infections for purposes of tissue remodeling and generally results in the downregulation of ECM syntheses such as collagen II and aggrecan." (PMID 36671243, 2022).
periodontal disease (1 paper, 2021). "ECM degradation is a key event in the early stages of periodontal disease, generating fragments that can act as danger-associated molecular patterns (DAMPs) such as fragmented aggrecan, fibronectin, biglycan, decorin and low molecular weight hyaluronic acid." (PMID 34255809, 2021).
phaeochromocytoma (1 paper, 2021). "Further investigations would be needed to uncover the relation between ACAN and phaeochromocytoma." (PMID 34905486, 2021). "But no direct evidence related to ACAN to phaeochromocytoma." (PMID 34905486, 2021).
polyarthritis (1 paper, 2025). "Proteoglycan-induced arthritis (PGIA) is induced by repeated immunizations with cartilage PG aggrecan in adjuvant, resulting in polyarthritis and subsequent articular cartilage and bone erosion." (PMID 40493163, 2025).
polyarticular JIA (1 paper, 2006). "To further elaborate on potential peptide-specific cytokine production, we generated short-term peptide-specific (aggrecan, fibrillin, or MMP-3) T-cell lines of PBMC from five patients with polyarticular JIA." (PMID 17129378, 2006).
polycystic ovary syndrome (1 paper, 2020). A disorder that manifests as multiple cysts on the ovaries. "Very low levels of aggrecan of 78 ng/ml have been reported in teenage participants with and without polycystic ovary syndrome (PCOS) (Tola, Koroglu, Yalcin, & Oral, 2018)." (PMID 32333524, 2020).
prostate tumours (1 paper, 2013). "Additionally, an aggrecan, syndecan-1, and glypican-1 expressions were detected in some prostate tumours." (PMID 23691363, 2013). "In this study, expression of cell surface and stromal proteoglycans (glypican-1, perlecan, syndecan-1, aggrecan, versican, NG2, brevican, decorin, and lumican) in normal tissue and prostate tumours was determined by RT-PCR analysis and immunostaining with core protein- and GAG-specific antibodies." (PMID 23691363, 2013). "Specific proteoglycans, absent in normal prostate tissue (aggrecan, NG2), were detected in some prostate tumours as well." (PMID 23691363, 2013).
retinal dystrophies (1 paper, 2021). "In hereditary retinal dystrophies, however, aggrecan is not involved in degenerative processes." (PMID 33668263, 2021).
salpingitis (1 paper, 2023). Acute or chronic inflammation of the fallopian tube. "In this study, HK2 and MOGAT1 were upregulated and CA4, CNTN3, and ACAN were downregulated in the CN-LPS group, suggesting that LPS-induced salpingitis caused abnormal lipid and sugar metabolism and altered the acid–base balance of the internal environment, degrading the extracellular matrix." (PMID 37978561, 2023).
Sciatica (1 paper, 2025). Pain in the lower back and hip radiating in the distribution of the sciatic nerve. "The aggrecan gene (ACAN) variant rs3817428 is linked to severity, while the 8q24.21 variant (rs6651255) is associated with sciatica in younger patients." (PMID 40654524, 2025).
selenium deficiency (1 paper, 2012). A nutritional deficiency disease resulting from inadequate selenium levels in the body, which can lead to impaired function of selenoproteins essential for antioxidant defense and thyroid hormone metabolism. "However, a recent rat study in our lab has shown that the depletion of aggrecan induced by T-2 toxin and selenium deficiency was mainly localised to the focal areas where cell death occurred, indicating a close relationship between PG loss and chondrocyte necrosis induced by mycotoxin." (PMID 22733148, 2012).
Short stature (1 paper, 2021). A height below that which is expected according to age and gender norms. "Since ACAN gene mutations are among the main causes of genetic short stature in the pediatric population, based on our findings, we believe that these should be considered also in the prenatal differential diagnosis of fetal growth’s delay in a fetus with short limbs." (PMID 34187405, 2021).
Spinal instability (1 paper, 2022). "In addition, spinal instability induces proteoglycan and collagen depletion, increasing the expression of messenger RNA for collagen, aggrecan, and perlecan." (PMID 35328395, 2022).
spondyloarthropathy (1 paper, 2012). A group of inflammatory rheumatic diseases associated with arthritis and enthesitis, and often involving the axial skeleton. "We recently discovered that uveitis develops in a murine model of spondyloarthropathy that arises from autoimmunity to the cartilage proteoglycan (PG) aggrecan, which is a proposed potential autoantigen in AS." (PMID 22269151, 2012).
ST Elevation Myocardial Infarction (1 paper, 2021). A myocardial infarction that produces elevation in the ST segments of the ECG. "We next analyzed ACAN plasma levels of patients with acute ST-elevation myocardial infarction (STEMI), which may confound the correct diagnosis of ATAAD." (PMID 33990642, 2021).
tauopathies (1 paper, 2022). "However, the biological basis for the selective vulnerability of neurons in tauopathies and the relation to neuroprotection by aggrecan remains elusive." (PMID 35454094, 2022).
uterine carcinoma (1 paper, 2014). A carcinoma involving a uterus. "In addition, aggrecan was expressed only in G2 and G3 uterine carcinomas." (PMID 25231141, 2014).
vascular tumors (1 paper, 2021). "Staining of aggrecan was variably and sometimes extensively positive in the vascular tumors as well as in the SBCs." (PMID 34081036, 2021).
ZIKV infection (1 paper, 2023). "Interestingly, ZIKV infection did not alter mRNA expression or total protein levels of aggrecan and brevican, however, it led to an increase in the cleaved forms of aggrecan and brevican proteins." (PMID 37496706, 2023).
skeletal dysplasia (24 papers, 2016 to 2025). Any Mendelian diseases that affects growth and development of the skeleton. "Mutations in ACAN can disrupt chondrocyte differentiation and endochondral ossification, contributing to skeletal dysplasias and early-onset OA." (PMID 39458144, 2024). "Mutations in the ACAN gene lead to various skeletal disorders and conditions, including some forms of short stature and skeletal dysplasia." (PMID 38396997, 2024). "This study enriched the genetic background of skeletal dysplasias, and expanded the mutation spectra of ACAN and PAPSS2." (PMID 35261200, 2022). "Mutations in ACAN were reported to be associated with growth defects ranging from mild idiopathic short stature to severe skeletal dysplasias." (PMID 33932142, 2021). "In this case report, we describe the first prenatal diagnosis of skeletal dysplasia associated with a pathogenic variant of ACAN." (PMID 34187405, 2021). "An examination by NGS of some genes associated with skeletal dysplasias showed a novel pathogenic variant of the ACAN gene: c.2677delG." (PMID 34187405, 2021). "In the postnatal life, heterozygous pathogenic sequence variations of the ACAN gene (coding for the proteoglycan aggrecan) were associated with evolutive growth defects, ranging from mild idiopathic short stature to severe skeletal dysplasias." (PMID 34187405, 2021). "Initially, ACAN mutations were associated with two rare types of skeletal dysplasias, one with an autosomal dominant (Spondyloepiphyseal dysplasia, Kimberley type) and another with a recessive inheritance (Spondyloepimetaphyseal dysplasia, aggrecan type)." (PMID 30864634, 2019). "ACAN defects are a common cause of idiopathic short stature and born small for gestational age; homozygous abnormalities result in severe skeletal dysplasia while heterozygous defects cause milder skeletal dysplasia." (PMID 31555216, 2019). "In this context, recent studies showed XYLT1 mutations to be causative for the manifestation of skeletal dysplasias, which could at least partially explain the reduced ACAN-expressions observed." (PMID 35563435, 2022). "Human diseases associated with ACAN mutations include osteochondritis and skeletal dysplasia." (PMID 33574040, 2021). "Several aspects of the aggrecan-deficient growth plate resemble those observed in Smad4-deficient growth plates, including skeletal dysplasia, loss of aggrecan expression, reduced chondrocyte proliferation, and deregulation of chondrocyte shape and organization." (PMID 28167493, 2017). "A notable aspect of this study was the frequency of heterozygous mutations detected in genes previously associated with skeletal dysplasia (NPR2, ACAN, CASR, COMP, and FBN1), confirming the dose effect of cartilage matrix proteins in growth and development." (PMID 37605180, 2023). "Genetic disorders associated with skeletal dysplasia include many genes involved in growth plate development, such as FGFR3, ACAN, NPR2, FBN1, and IHH, which can cause varying degrees of short stature with or without other minor abnormalities." (PMID 35250876, 2022). "In case of suspicion of skeletal dysplasia, the ACAN gene should be considered." (PMID 34187405, 2021). "Heterozygous mutations of the ACAN gene are a major cause of different evolutive growth defects in the pediatric population, but were never described as a cause of fetal skeletal dysplasia." (PMID 34187405, 2021). "In 2014, heterozygous ACAN mutations were identified as cause of short stature in three families with no skeletal findings suggestive of skeletal dysplasia." (PMID 30864634, 2019). "Heterozygous mutations of the ACAN gene have been associated with a broad spectrum of non-lethal skeletal dysplasias, called Aggrecanopathies." (PMID 31747937, 2019).
skeletal dysplasia (continued). "In addition, for the general short-stature population with skeletal dysplasia, ACAN-related short stature was more responsive to rhGH treatment than NPR2-related short stature, and significant height improvement was not seen in FGFR3-related short-stature patients in this cohort." (PMID 35250876, 2022). "This study expands the genotypic–phenotypic spectra of ACAN and PAPSS2, and highlights the important role of ACAN in short stature‐related skeletal dysplasia." (PMID 35261200, 2022). "While mutations in structural protein genes like ACAN and COL2A1 are linked to skeletal dysplasia and early-onset OA, they are not directly associated with the more common late onset idiopathic OA." (PMID 39458144, 2024).
tumor (16 papers, 2012 to 2025). "Raman imaging and immunohistochemical staining of representative tumor samples across clinical stages revealed prominent presence of type I collagen, hyaluronan, aggrecan, and laminin." (PMID 40416783, 2025). "MMP13 cleaves multiple collagens as well as other extracellular matrix (ECM) substrates such as gelatin, fibronectin, and aggrecan relevant to tumor metastasis." (PMID 40839695, 2025). "When U-CH1 cells were maintained in hypoxia, we found an increase in the expression of notochord markers (T, CD24, FOXA1, ACAN and CA12), tumour-sphere formation and cell growth, and a decrease in cell migration." (PMID 25541962, 2014). "Several matrix metalloproteinases (MMPs) were up-regulated in tumour samples, namely MMP12 (5.1-fold), MMP14 (2.3-fold) and MMP2 (2.2-fold), which cleave elastin (and insulin), collagen (and other extracellular proteins, such as aggrecan) and certain collagens (and gelatin), respectively." (PMID 37397358, 2023).
cancer (15 papers, 2013 to 2026). A tumor composed of atypical neoplastic, often pleomorphic cells that invade other tissues. "ACAN and VCAN were not only associated with extracellular matrix composition but were also expressed higher in cancer patients." (PMID 37108649, 2023). "Aggrecan is a member of the proteoglycans and influences the adhesive and mitotic activity of cancer cells." (PMID 25231141, 2014). "There is also some evidence that aggrecan depletion that occurred in cartilaginous tissues in cancer progression is mediated through the action of ADAMTS, and especially ADAMTS-5." (PMID 25105124, 2014). "The fact that aggrecan was expressed only in grades 2 and 3 suggests that it may be a biomarker for cancer progression in a clinical setting." (PMID 36982551, 2023). "ADAMTS 9 degrades aggrecan and versican in cancer cells, which are important components of its ECM." (PMID 36982551, 2023). "Aggrecan contributes to the adhesive and mitotic activity of cancer cells." (PMID 36982551, 2023). "Moreover, ACAN has a tight link with the occurrence and development of cancer." (PMID 38467737, 2024). "The results showed that the expression of ACAN and VCAN was significantly higher in cancer patients than in normal patients (p < 0.01)." (PMID 37108649, 2023). "Over-expression of these proteases is consistent with the requirements of carcinoma cells to remove proteoglycans of ECM, such as versican and aggrecan, as a complementary mechanism to collagen degradation by collagenases and gelatinases." (PMID 25786261, 2015). "A similar trypsinogen secreted from cancer cell lines, degrades subendothelial cell extracellular matrix (ECM) and it has been shown that enzymes similar to PRSS3 degrade fibronectin and aggrecan." (PMID 23437119, 2013). "Almost all variants of SYNE2, ACAN, and PDZD7 genes identified in our patients had not been shown to be of clinical importance with regard to cancer biology." (PMID 35884495, 2022). "SOX6 directly activates transcription of aggrecan (Acan) and expression of MMP12 in cancer tissue." (PMID 34440750, 2021). "Some other proteoglycans such as aggrecan, neurocan, brevican, biglycan, lumican, glypicans, fibromodulin, agrin, collagen XVIII, NG2, and serglycin are also involved in cancer progression, but their expression and functional role have not yet been investigated in prostate cancer." (PMID 23691363, 2013). "MMPs have also shown that they participate in cartilage destruction in cancer, but it is not clear whether they attack aggrecan." (PMID 25105124, 2014).
metabolic disorder (7 papers, 2020 to 2025). "The ACLT group exhibited reduced expression of PPAR‐γ, GLUT1, aggrecan, and collagen II, alongside increased collagen I expression, indicating chondrocyte metabolic disorders and phenotypic loss." (PMID 40008494, 2025). "During the progression of IDD, the gradual loss of collagen II and aggrecan due to NP ECM metabolic disorder leads to a decrease in IVD height, loss of the boundary between the AF and NP, and a decline in the ability to withstand mechanical loads." (PMID 35308165, 2022). "In this study, Glycitin effectively reversed the TNF-α-mediated loss of Col-2 and Aggrecan, and reduced the level of MMP-13 and ADAMTS-5, suggesting that Glycitin is a key role in metabolic disorders of IVD." (PMID 38019477, 2023). "The expression of ITGA4, the receptor for the VCAN ligand, was downregulated in C1, a condition favoring the ACAN metabolic disorder found in C1." (PMID 33298863, 2020). "Then qPCR and Western blotting revealed that Se-Met supplementation reduced the production of ADAMTS-5 and MMP-13 and promoted the secretion of Aggrecan and Col-2 in response to mechanical overloading, while additional ML210 aggravated ECM metabolic disorder." (PMID 38252317, 2024). "Positive staining for ACAN in the articular cartilage was significantly higher in C1 patients, while MMP13-positive cells dominated the collagen metabolic disorder C2 subtype." (PMID 33298863, 2020). "Besides, the qPCR and Western blotting revealed that Se-Met supplementation reduced the production of ADAMTS-5 and MMP-13, and promoted the secretion of Aggrecan and Col-2, while knockdown of SelK aggravated ECM metabolic disorders." (PMID 38252317, 2024).